PDCD1 (programmed cell death 1)
Diseases named in the same sentence as PDCD1 in open-access papers (continued):
Sharing a sentence is not in itself a finding about the gene and the disease.
Autoimmunity (64 papers, 2009 to 2025). The occurrence of an immune reaction against the organism's own cells or tissues. "Recently, a homozygous loss-of-function mutation in PDCD1 was identified in a child manifesting with multiorgan autoimmunity and Mycobacterium tuberculosis infection, which suggested inherited complete PD-1 deficiency." (PMID 37261359, 2023). "In 2021, a homozygous frameshift variant of PDCD1 was identified in a child who was born to consanguineous Turkish parents and suffered from severe TB and autoimmunity." (PMID 36569938, 2022). "In humans, polymorphisms in the gene for PD-1, programmed death cell protein 1 (PDCD1), are associated with an increased risk of autoimmunity as well, including early-onset lupus." (PMID 34201529, 2021). "Certain single nucleotide polymorphisms (SNPs) in the PDCD1 gene, which codes for PD-1, are also associated with a variety of autoimmune disorders, including RA, SLE, diabetes mellitus, and MS, in different ethnic groups." (PMID 34063096, 2021). "In humans regulatory polymorphisms in the PDCD1 gene are associated with susceptibility to a variety of autoimmune conditions including systemic lupus erythematosus, atopy and rheumatoid arthritis, and progression in multiple sclerosis (MS)." (PMID 30349540, 2018). "Greater than 30 single nucleotide polymorphisms (SNPs) have currently been identified in the human PDCD-1 gene, and several SNPs have been linked to development of autoimmunity in various populations." (PMID 24804191, 2014). "In addition, mutations in the PDCD1 gene are associated with susceptibility to several human autoimmune disorders." (PMID 39062968, 2024). "Programmed cell death 1 (PD‐1) is an immunosuppressive factor associated with autoimmune disorders." (PMID 33516274, 2021). "Additionally, in the PDCD1 gene, single nucleotide polymorphisms have been reported in patients suffering from peripheral autoimmune disorders, such as RA, type 1 diabetes (T1D), and systemic lupus erythematosus (SLE)." (PMID 34298735, 2021). "It is supposed that PD-1 deficiency could promote tissue-specific autoimmunity inherent in the strain by favoring the activation of those T cells that in Pdcd1+/+ mice were found anergic." (PMID 30386337, 2018). "Autoimmune checkpoint molecule programmed cell death 1 (PD-1), expressed by T cells, B cells and other immune cells, plays a crucial role in maintaining immune tolerance and autoimmunity prevention by downregulating immune responses." (PMID 41376634, 2025). "The protein encoded by CD274 is a ligand, also known as the Programmed death-ligand 1 (PD-L1), which interacts with its receptor the programmed cell death-1 (PD-1) to inhibit cytokine production and prevent autoimmunity, thereby maintaining immune homeostasis." (PMID 41272439, 2025). "Programmed cell death 1 (PD-1) is expressed in T cells to suppress peripheral autoimmunity (immune tolerance)." (PMID 37409245, 2023). "Pdcd1 gene knockout mice (PD-1KO) have been useful to elucidate the function of PD-1 in central and peripheral tolerance and development of autoimmunity." (PMID 34912335, 2021). "When the programmed cell death-1 (PD-1)/PD-L1 axis is highly expressed in a healthy immune system, activation of this pathway restricts autoimmunity and limits T-cell activity in an inflammatory response to infection." (PMID 32337367, 2020). "The immune co-inhibitory receptors lymphocyte activation gene-3 (LAG3) and programmed cell death 1 (PD1) synergistically contribute to autoimmunity and tumor evasion." (PMID 26318293, 2015). "PDCD1 is expressed by activated T cells, B cells as well as natural killer (NK) cells and upregulated on T cells after persistent antigen exposure, preventing autoimmunity." (PMID 37215135, 2023). "Immune checkpoints, represented by programmed cell death-1 (PD-1) and cytotoxic T-lymphocyte-associated protein-4 (CTLA-4), are inhibitory regulators in the immune system, facilitating the maintenance of peripheral tolerance and preventing autoimmunity." (PMID 35494073, 2022).
Autoimmunity (continued). "Programmed cell death-1 (PD-1) together with PD-L1 (the ligand of PD-1) are regulatory molecules with negative costimulatory signals and evoke vital function in modulating various aspects of the immune system, such as infection immunity, autoimmunity, and tumor immunity." (PMID 35600045, 2022). "The interaction between dendritic cells (DCs) and T cells mediated by the programmed cell death 1 (PD-1)/programmed cell death ligand 1 (PD-L1)/programmed cell death ligand 2 (PD-L2) pathway is the most important point in regulating immunological tolerance and autoimmunity." (PMID 36232911, 2022). "Nivolumab, an anti-programmed cell death-1 (PD-1) antibody, has emerged as a breakthrough medication for several advanced malignancies; however, it frequently induces thyroid dysfunction, possibly by evoked autoimmunity, similar to other immune-related adverse events (irAEs)." (PMID 29884162, 2018). "Programmed cell death 1 (PD1) protein, acts as an immune checkpoint, and has an important role in the down-regulation of the immune system by preventing the activation of T-cells, which will weaken the autoimmunity and increases self-tolerance." (PMID 39090421, 2025). "Recent years, PDCD1 (PD-1), CD274 (PD-L1) and CTLA4 have been confirmed to act as immune checkpoints and can prevent the immune system from killing cancer cells by inhibiting autoimmunity." (PMID 36845098, 2023). "PDCD1 is a ligand of CD274 and is involved in safeguarding against autoimmunity." (PMID 36158806, 2022). "Importantly, these mice did not succumb to cytokine storm or systemic autoimmunity, as seen in Ctla4 or Pdcd1 null mice, and had limited inflammation in extraneous tissues." (PMID 39247203, 2024).
renal cell carcinoma (63 papers, 2015 to 2026). "Since, according to our best knowledge, our study is the first that analyzed PDCD1 and PD-L1 gene polymorphisms in the context of renal cell cancer, further studies will be needed in order to determine whether rs7421861T>C polymorphism may be considered to be a risk factor for this type of cancer." (PMID 33255938, 2020). "Pembrolizumab, a monoclonal antibody targeting programmed cell death-1 (PD-1), plays a pivotal role in modern oncology, including both adjuvant and advanced settings for renal cell carcinoma." (PMID 41441532, 2025). "Immunotherapies that target programmed cell death-ligand 1 (PD-L1) or programmed cell death-1 (PD-1) inhibitors have become cornerstones of treatments for malignant tumours such as gastrointestinal, pulmonary, renal cell carcinoma, and melanoma." (PMID 31992245, 2020). "Thus, anti-programmed cell death-1/programmed cell death-ligand 1 (PD-1/PD-L1) antibody has been approved for second-line or first-line treatment in melanoma, renal cell carcinoma, head and neck squamous and gastroesophageal cancer." (PMID 33066479, 2020). "Recently, with the promising efficacy of anti-programmed cell death-1/ligand-1 (PD-1/PD-L1) inhibitor in melanoma, NSCLC, renal cell cancer, and other solid tumors, a variety of clinical trials have been performed to estimate the antitumor performance of immunotherapy in SCLC." (PMID 34777341, 2021). "Immunotherapies targeting cytotoxic T lymphocyte antigen 4 (CTLA-4) and programmed cell death 1 (PD-1) have been used for the treatment of melanoma, non-small cell lung cancer (NSCLC), renal cell carcinoma (RCC), and Hodgkin's lymphoma 14-21." (PMID 40861815, 2025).
autoimmune disease (55 papers, 2006 to 2026). "It is well known that genetic polymorphisms of CTLA4 and PDCD1 genes can increase the risk of developing autoimmune diseases, including IIHs." (PMID 41465179, 2025). "After integrating the data of SLE, RA, and GO, it was found that rs11571315, rs733618, rs4553808, rs16840252, and rs11571319 of CTLA4 and rs36084323 of PDCD1 had a significant statistical association in these three autoimmune diseases." (PMID 37760867, 2023). "The pathomechanism of various autoimmune diseases is known to be associated with the altered function of programmed cell death 1/programmed cell death ligand 1 (PD-1/PD-L1) axis." (PMID 35979531, 2022). "In human beings, the manifestation of autoimmune diseases has been associated with PDCD1 gene polymorphisms; examples are rheumatoid arthritis, systemic lupus erythematosus, and multiple sclerosis." (PMID 36230402, 2022). "Pdcd1-deficient animals showed impaired control of IgA, microbial dysbiosis, and strain-dependent autoimmune disease susceptibility, similar to Btla-deficient strains." (PMID 35320716, 2022). "For example, gene polymorphisms in Pdcd1 are associated with the susceptibility of autoimmune diseases including rheumatoid arthritis (RA), type 1 diabetes mellitus (T1DM), systemic lupus erythematosus (SLE), ankylosing spondylitis (AS) and MS." (PMID 34480337, 2021). "Studies have shown that SNPs in PDCD1 are associated with a number of autoimmune diseases, including SLE, RA, T1D, and ankylosing spondylitis (AS)." (PMID 34381337, 2021). "Polymorphisms of programmed cell death 1 (PDCD-1) gene are associated with autoimmune diseases, cancers, and viral infections." (PMID 34571982, 2021). "In humans, single-nucleotide polymorphisms (SNP) of the PDCD1 gene have been connected with different autoimmune diseases, such as systemic lupus erythematosus." (PMID 32265932, 2020). "Accordingly, different genetic polymorphisms of the PD-1 gene (PDCD1) have been associated with autoimmune disease, including type-1 diabetes mellitus and systemic lupus erythematosus." (PMID 30546030, 2018). "Association between SNPs in PDCD1 and disease susceptibility to autoimmune diseases were demonstrated in SLE, Type I diabetes, RA, MS, and Graves disease." (PMID 24350294, 2013). "PDCD1 is a cell surface receptor that regulates T-cell proliferation and activation, which was linked in earlier studies to autoimmune diseases like type 1 diabetes and rheumatoid arthritis." (PMID 20885778, 2010). "Germline CTLA4 and PDCD1 gene polymorphisms are associated with autoimmune diseases." (PMID 35912205, 2022). "Moreover, it has been established that mutations in the human CTLA4 and PDCD1 loci are associated with various autoimmune diseases." (PMID 30201974, 2018). "In addition, genetic studies revealed that there is an association between PDCD-1 gene polymorphism and susceptibility to autoimmune diseases, such as systemic lupus erythematosus (SLE), rheumatoid arthritis, multiple sclerosis, and diabetes mellitus." (PMID 24804191, 2014). "The inhibitory ICP receptor programmed cell death 1 (PD-1) is expressed on activated T cells in infections, malignancies, and autoimmune diseases." (PMID 37946301, 2023). "Expressed on T-cells, B cells, and NK cells, programmed cell death 1 (PD-1) is a checkpoint that keeps the immune response in check to prevent autoimmune diseases and immune overactivation 118,119." (PMID 34729098, 2021). "Recently, it has been reported that immune checkpoint inhibitors, such as programmed cell death-1 (PD-1) and programmed death-ligand 1 (PD-L1) activate T cells and can induce autoimmune-disease-like symptoms." (PMID 33833871, 2021). "The programmed cell death 1 (PD-1) protein is a critical regulator of T-cell activation and is also an important therapeutic target for autoimmune diseases." (PMID 26608464, 2015).
autoimmune disease (continued). "Overlapping of some gene locations of different autoimmune diseases has been known and supports common pathogenic gene variants (PTPN 22, Csk, PAG, PSTPIP1, PDCD1, SLC9A3R1, CARD15, and SUMO4) transcript within these diseases." (PMID 26339139, 2015). "Previous experiments on knockout mice revealed that the PDCD1/CD274 system has most likely evolved as means to ensure immunological tolerance to self-tissue, as mice deficient in PDCD1 suffer from spontaneous autoimmune diseases." (PMID 25940792, 2015). "In contrast, PD1 knockout (Pdcd1 −/−) mice, develop various types of autoimmune diseases depending upon the background." (PMID 26318293, 2015). "In addition, Pdcd1−/− mice develop severe autoimmune disease by 9–10 mo, and thus these experiments used knockout mice that were at most 10 mo of age." (PMID 38015461, 2023). "Mice deficient in PDCD-1 developed spontaneous autoimmune diseases, which suggested a negative costimulatory function." (PMID 28415570, 2017). "Moreover, PDCD1 may also be important in T cell function and contribute to the prevention of autoimmune diseases." (PMID 31281315, 2019). "PDCD1, like CTLA4, plays a negative regulatory role in T-cell activation to develop immune tolerance, which can prevent the development of autoimmune diseases or prevent the immune system from killing cancer cells." (PMID 34671352, 2021). "Programmed cell death 1 (PD-1; also known as PDCD1) and programmed death-1-ligand 1 (PD-L1; also known as CD274) play important negative regulatory roles in inflammation, autoimmune diseases, and tumors." (PMID 33521133, 2021). "Notably, both HLA-I-specific and HLA-II-specific pGenes included known drug targets for autoimmune diseases, infectious diseases, and cancer such as LAG3, PDCD1, TNF, and ACE2 affected by HLA-I; and IL18, TREM2, VSIG4, and TLR1 by HLA-II." (PMID 39085222, 2024).
bladder cancer (47 papers, 2017 to 2025). "The immune checkpoint molecules, such as programmed cell death 1 (PD-1), PD-1 ligand 1 (PD-L1) and cytotoxic T-lymphocyte associated antigen 4 (CTLA-4), have demonstrated a remarkable, durable response in bladder cancer, prostate cancer and kidney cancer." (PMID 35143414, 2022). "Despite the efficacy of immune checkpoints, including programmed cell death-1 (PD-1) and cytotoxic T-lymphocyte-associated protein 4 (CTLA-4), the effect of immunotherapy for bladder cancer remains unsatisfactory." (PMID 35069212, 2021). "Since the expression of TIGIT and PDCD1 on the CD8 T cells are widely used to identify dysfunction or early activated effector T cells in several cancer types such as bladder cancer, these markers alone are insufficient to define terminally exhausted CD8+ T cell in CRC." (PMID 40799645, 2025). "Anti-programmed cell death 1/programmed cell death ligand 1(PD-1/PD-L1) inhibitors were recommended in clinical guidelines as first and second-line treatments for select patients with advanced bladder cancer." (PMID 38961326, 2024). "Notably, PDLIM2 expression was strongly correlated with TIM-3 in bladder cancer and with PDCD1, CTLA4, GZMB, and LAG3 in KIRP." (PMID 35121770, 2022). "Though the signature was only significantly associated with ICI-related biomarkers like TNFRSF9, instead of CTLA4, LAG3, HAVCR2 and PDCD1, thus proving that the efficacy of immunotherapy still presents an underprivileged position within the treatment of bladder cancer." (PMID 34322391, 2021). "Our data indicated that bladder cancer patients with high TstcSig exhibited “hot tumor” characteristics, characterized by a higher proportion of infiltrating immune cells, elevated immune scores, and increased expression of immune checkpoint genes such as PDCD1, CDLA4, LAG3, and CD274." (PMID 39033098, 2024). "Programmed cell death 1 (PD-1, also known as CD279), programmed cell death 1 ligand 1 (PD-L1, also known as CD274), and CTIL-4, are common immune checkpoints, have been described in bladder cancer." (PMID 33604353, 2020). "In particular, Programmed Cell Death 1 (PD-1) seems to play a critical role in preventing tumor rejection and PD-1 blocking antibodies have shown impressive activity in melanoma, NSCLC, and bladder cancer, among others." (PMID 29755681, 2018). "As main immunotherapeutic options, programmed cell death 1 (PD1), PD1 ligand (PDL-1), and cytotoxic T-lymphocyte antigen 4 (CTLA-4) expression might be served as potential factors for individual selection of treatment with immune checkpoint inhibitors for bladder cancer patients." (PMID 37968767, 2023).
glioblastoma (40 papers, 2017 to 2025). The most malignant astrocytic tumor (WHO grade IV). "Sotuletinib (BLZ945) is a brain-penetrant, oral CSF1R inhibitor that has demonstrated a reduction in TAM recruitment, tumour growth, and resistance to programmed cell death 1 (PD-1) inhibitors in animal models of intracranial glioblastoma multiforme (GBM)." (PMID 37711590, 2023). "Numerous studies have shown significantly higher levels of PDCD1 in glioblastoma tissues as compared with normal brain tissues." (PMID 36428756, 2022). "Wilms’ tumor gene 1 (WT1) peptide vaccine and anti-programmed cell death-1 (anti-PD-1) antibody are expected as immunotherapies to improve the clinical outcome of glioblastoma." (PMID 34355173, 2021). "Immunotherapies targeting tumour-infiltrating lymphocytes (TILs) that express the immune checkpoint molecule programmed cell death-1 (PD-1) have shown promise in preclinical glioblastoma models but have had limited success in clinical trials." (PMID 34676050, 2021). "The innate immune system, instead of CD8+T cells, might have greater responsibility for the therapeutic effects of anti- programmed cell death-1 (PD-1) antibodies in glioblastoma." (PMID 36119521, 2022). "Among them, IDO1, PDCD1, and TGFB1 are promising immune-modulatory targets that are in the focus of current clinical research in glioblastoma." (PMID 35734424, 2022). "The T cell population in glioblastoma generally displays a profoundly exhausted phenotype, characterised by expression of LAG3, TIGIT, CD39 and especially programmed cell death 1 (PD1)." (PMID 33803414, 2021). "Programmed cell death-1 (PD-1) is a cell surface immune checkpoint found on effector T cells, while its ligand, PD-L1, can be expressed by glioblastoma cells, with elevated PD-L1 being associated with poor overall survival in glioblastoma patients, independent of other factors." (PMID 30568917, 2018). "Despite Glioblastoma (GBM) frequently expressing programmed cell death ligand-1 (PD-L1), treatment with anti-programmed cell death-1 (PD1) has not yielded brilliant results." (PMID 34572014, 2021).